RNU2-66P (RNA, U2 small nuclear 66, pseudogene)
Gene: Small nuclear RNA gene on chromosome 4 (154,787,118 to 154,787,278, forward strand). Ensembl gene ENSG00000222582.
Homologues: Orthologues: chimpanzee U2 (73% identical), macaque U2 (62% identical), mouse Gm25475 (56% identical), rat LOC120094028 (52% identical), rabbit U2 (45% identical). Paralogues in human: RNU2-2 (66% identical), U2 (65% identical), RNU2-59P (65% identical), RNU2-14P (64% identical), RNU2-23P (64% identical), RNU2-4P (64% identical), RNU2-56P (64% identical), RNU2-52P (63% identical), RNU2-6P (63% identical), RNU2-3P (62% identical), RNU2-64P (62% identical), RNU2-8P (62% identical), and 64 more.